AR (androgen receptor)
Diseases named in the same sentence as AR in open-access papers (continued):
Sharing a sentence is not in itself a finding about the gene and the disease.
prostate carcinoma (continued). "The androgen receptor (AR) signaling pathway plays a critical role in prostate cancer development and progression, and is also involved in regulating the tumor immune microenvironment (TIME)." (PMID 37646236, 2023). "Our data indicate that the isolated alkaloid and its derivatives are capable of potentizing the efficacy of AR-targeting agents in treatment resistant prostate cancer, suggesting further preclinical and clinical development." (PMID 36662227, 2023). "The main molecular signaling pathways of prostate cancer are the androgen receptor (AR) mediated signaling pathway, NF-κB, PI3K/AKT, MAPK, TGF-β/SMAD, JAK/STAT, and Wnt signaling pathway." (PMID 38188680, 2023). "In a more recent study, a microRNA miR-31-3p was shown to suppress the growth of prostate cancer cells via directly downregulating GABBR2 expression similarly in AR-positive and AR-negative lines." (PMID 37762034, 2023). "Castration-resistant prostate cancer (CRPC) consists of multiple phenotypic subtypes including androgen receptor (AR)-active prostate cancer (ARPC) and neuroendocrine prostate cancer (NEPC)." (PMID 37823778, 2023). "With better insights into androgen receptor (AR) signaling and the emergence of castration-resistant prostate cancer, novel agents targeting the AR pathway have emerged." (PMID 37686423, 2023). "Type I and type III 5α-reductase (SRD5A1 and SRD5A3) were discovered to be correlated with DHT generation and AR activation in malignant prostate tumors, while type II (SRD5A2) is primarily expressed in normal prostate tissues." (PMID 37152995, 2023). "Altogether, these data suggest that SPA inhibits growth of prostate cancer with high AR abundance in part through downregulation of MYC." (PMID 36194476, 2022). "Altogether, this strongly suggests that FOXA1’s pioneering activity contributes to prostate cancer tumorigenesis by influencing the AR cistrome." (PMID 36212399, 2022). "In prostate cancer, abnormal activation of androgen receptor (AR) signaling is the essential characteristic for cancerous cells to maintain survival and to proliferate continually." (PMID 36523976, 2022). "Anti-AR therapy can be used as a therapeutic strategy and preventive option in patients with prostate cancer to inhibit the entry of viruses." (PMID 35017320, 2022). "For instance, expression of the lncRNA HOTAIR is up-regulated by androgen deprivation, thus, leading to AR stabilization, and this promotes prostate cancer growth, invasion and metastasis." (PMID 35682963, 2022). "It recapitulates key aspects of prostate cancer, such as stimulation by androgen and inhibition by AR antagonist." (PMID 36611998, 2022). "Treatment with the DNA demethylating agent 5-aza-2’-deoxycytidine (5-aza) reactivated AR expression, prevented the development of poorly differentiated prostate cancer and lymph node metastases, and significantly extended survival vs. control-treated mice." (PMID 35909568, 2022). "Numerous coregulators of AR have previously been identified, not only in regulating the activation of the AR pathway but also in regulating the proliferation of prostate carcinoma cells." (PMID 35444697, 2022). "Since then, prostate cancer treatment has been mainly focused on reducing androgen levels and blocking androgen-induced AR activation." (PMID 35372068, 2022). "MiR-654-5p was among fifteen AR downregulating miRNAs that decreased androgen-induced proliferation of prostate cancer cells." (PMID 36091792, 2022). "Following androgen receptor pathway inhibition prostate cancers can differentiate towards the neuroendocrine lineage." (PMID 35477723, 2022). "Advanced prostate cancers display AR hyperactivation and transcriptome expansion, in part, through AR amplification and interaction with oncoprotein cofactors." (PMID 35447082, 2022).
prostate carcinoma (continued). "Although the AR roles in CAFs are still unclear, it has been shown that prostate cancer epithelial growth, invasion, and colony formation abilities decreased when knocking down the CAFs AR." (PMID 35885510, 2022). "Treatment with androgen receptor pathway inhibitors (ARPIs) in prostate cancer leads to the emergence of resistant tumors characterized by lineage plasticity and differentiation toward neuroendocrine lineage." (PMID 35477723, 2022). "In summary, our transcriptome profile analysis, immunohistochemistry staining, and multiplex fluorescence staining together demonstrate the existence of AR and NE double-high prostate cancer." (PMID 36033483, 2022). "In particular, Androgen Receptor (AR) is a transcription factor whose activity is highly critical to prostate cancer evolution." (PMID 35565241, 2022). "PBK was reported to regulate the expression of androgen receptor (AR) protein, and the overexpression of PBK in aggressive prostate cancer was reported to be associated with early biochemical relapse and poor clinical manifestations." (PMID 35360870, 2022). "We have shown that carbidopa as an AhR agonist attenuates pancreatic cancer growth while other investigators have shown that carbidopa suppresses prostate cancer growth via AhR-mediated ubiquitination and degradation of androgen receptor." (PMID 35997090, 2022). "It has been shown that iCRT3, a Wnt inhibitor, can also disrupt the interaction between AR and β-catenin and repress AR-mediated transcription and growth in prostate cancer cells." (PMID 35902588, 2022). "This combination therapy suppressed AR and Bcl-2 expression, AR translocation into the prostate cancer cell nucleus, and AR signaling." (PMID 35582529, 2022). "Although primarily demethylating H3K4me1/me2, LSD1 was reported to demethylate the repressive methylated H3K9mark in prostate cancer and thus enhance the function of the androgen receptor (AR)." (PMID 35406676, 2022). "It has been reported that emodin can directly target AR to inhibit the growth of prostate cancer cells and prolong the survival time of tumor-bearing mice." (PMID 35637953, 2022). "Our data demonstrated that Remodelin, an inhibitor of NAT10, effectively inhibits the proliferation, migration, and invasion of PCa cells in both AR-positive and AR-negative prostate cancer cells." (PMID 35743017, 2022). "The predictive value of AR in tumor response has been clearly observed following AR-directed therapy in prostate cancer, but its predictive role in the treatment of TNBC is still to be determined." (PMID 35711833, 2022). "Considering that prostate cancer cells that develop resistance to AR-targeted therapy usually maintain AR expression, the interplay between MYC and AR is likely to remain critical as the disease progress to the CRPC stage." (PMID 35562350, 2022). "While hZimp10 was only confirmed to stimulate the SUMOylation of AR, this SUMOylation enhanced the transcriptional activity of AR in human prostate cancer cells." (PMID 35408996, 2022). "Updated research has demonstrated that the RNA helicase DEAH-box (DHX) 15 stabilizes E3 ligase Siah2 and enhances Siah2 activity, thus ubiquitinates and degrades AR, whereas enhanced AR transcriptional activity contributes to prostate cancer progression." (PMID 35002522, 2022). "At present, our understanding of the extent to which metformin suppresses growth and intracellular signaling in AR-positive, castration-resistant prostate cancers is limited." (PMID 36175875, 2022). "Here, we show that growth inhibition of prostate cancer models by SPA required high androgen receptor (AR) activity and were driven in part by downregulation of MYC." (PMID 36194476, 2022). "FT-7051 is an orally available, effective, and selective CBP/p300 inhibitor that has shown promise in preclinical models of prostate cancer, particularly those resistant to AR inhibitors like enzalutamide." (PMID 36034650, 2022).
prostate carcinoma (continued). "Androgen receptor (AR) signaling remains the key therapeutic target in the management of hormone‐naïve‐advanced prostate cancer (PCa) and castration‐resistant PCa (CRPC)." (PMID 34919781, 2022). "The inhibition of PyK2 expression attenuated the growth of prostate cancer cells and down-regulated androgen receptor expression and activity." (PMID 36555115, 2022). "The SWI/SNF complex is a known cofactor of the AR and contributes to AR-dependent gene regulation in prostate cancer." (PMID 36212399, 2022). "Androgen receptor (AR) signaling is the most important therapeutic target in prostate cancer, and emerging evidence suggests that AR also regulates a network of DNA repair genes." (PMID 35163621, 2022). "Previous studies have noted AR activation suppresses the expression of the glucocorticoid receptor (GR) in prostate cancers." (PMID 36175875, 2022). "Using multiplex immunofluorescence staining, we observed the co-localization of AR and NE markers in prostate cancer cells." (PMID 36033483, 2022). "Although AR signaling is active at all stages of prostate cancer, our ChIP-seq analysis illustrated differential epigenetic regulation of B7-H3 transcripts in mCRPC compared to primary prostate cancer." (PMID 36323882, 2022). "This assay is designed to mimic a clinical situation in which prostate cancer is highly expressing full-length AR and AR-V7." (PMID 35087237, 2022). "Previous studies with bipolar androgen therapy (BAT) have shown clinical activity in metastatic Castration Resistant Prostate Cancer (mCRPC) as well as the potential to re-sensitise prostate cancer cells to prior androgen receptor-targeted agents." (PMID 36819799, 2022). "Correlation between PDHA complex components and androgen receptor protein expression in prostate cancer." (PMID 35692804, 2022). "In the case of androgen receptor (AR), activation of AR by androgen is known to be involved in the progression of prostate cancer, and antiandrogen drugs that block the binding are used for treatment." (PMID 37435453, 2022). "A positive correlation between the expression of FLII and overall survival of prostate cancer patients expressing high levels of AR expression was shown by a clinical gene expression array dataset." (PMID 35756667, 2022). "Interactions between AR-activated enhancers and promoters leading to downstream gene activation have been studied in detail in prostate cancer cell lines." (PMID 35682963, 2022). "Several findings regarding DJ-1 activity have highlighted that the regulation of the AR signaling pathway is another important DJ-1 role, and a useful biomarker for several cancer types, including prostate cancer." (PMID 35563738, 2022). "AKR1C3, a crucial androgenic enzyme, plays a role in recoding the AR signal transduction in prostate cancer." (PMID 36276091, 2022). "The loss of PTEN, resulting in tumorigenesis or drug resistance due to a hyperactivation of the PI3K/Akt/mTOR pathway, is the second most common genomic aberration in advanced prostate cancer after the androgen-receptor (AR) alterations." (PMID 36077726, 2022). "Further investigation reveals the role of AR as an upstream mediator of MIR17HG, so that silencing AR decreases MIR17HG expression in prostate cancer cells." (PMID 35317831, 2022). "The candidate compound, 24j (17R)-17-((3-(2-hydroxypropan-2-yl)isoxazol-5-yl)methyl)-androst-5-en-3β-ol, suppressed the androgen receptor signaling and decreased its protein level in two prostate cancer cell lines, LNCaP and LAPC-4." (PMID 36362320, 2022). "Prostate cancer (PCa) growth and progression are driven by the androgen receptor (AR) signaling pathway." (PMID 36429059, 2022).
prostate carcinoma (continued). "Androgen receptor (AR)-mediated transcription is critical in almost all stages of prostate cancer (PCa) growth and differentiation." (PMID 35269520, 2022). "It was identified as an inhibitor of the androgen receptor (AR), which can inhibit the growth of androgen-sensitive prostate cancer cells by binding with the activation function-1(AF-1) region of AR." (PMID 36555703, 2022). "ADT inhibits activation of the transcription factor and primary driver of prostate cancer, the androgen receptor (AR)." (PMID 35741020, 2022). "In the prostate cancer cell line LNCaP, the AR was found to bind to response elements present in approximately the first 80 kb upstream of TMPRSS2." (PMID 36560732, 2022). "Shin and colleagues first reported that JMJD2D is a novel AR coactivator, which can form a complex with ligand-bound AR via its C-terminus to promote the progression of prostate cancer." (PMID 35740507, 2022). "In this study, we report a novel method exploiting bioluminescence microscopy to detect single prostate cancer (PCa) cell response to androgen receptor (AR)-axis-targeted therapies (ARAT) and predict cell population sensitivity." (PMID 34976196, 2022). "Accumulated evidence has suggested AR as a master of metabolic reprogramming in prostate cancer cells." (PMID 36551308, 2022). "AR activity is well established as a dependency of prostate cancer (PCa) throughout all stages of growth and progression, leading to the essential role of AR-directed therapies for PCa." (PMID 36376977, 2022). "The AR protein is a nuclear receptor expressed in benign and malignant prostate tissues, critical for prostate physiological functionality and prostate cancer progression." (PMID 35372068, 2022). "HG122 suppressed AR-positive prostate cancer cell growth with an IC50 of 7-9 μM, compared to AR-negative cells at 20 μM." (PMID 35372068, 2022). "Another study has indicated that SF3B2 can affect the resistance of prostate cancer to AR targeting therapy by affecting the AS events of the AR gene." (PMID 35126520, 2022). "Researchers have observed the taxane-dependent inhibition of AR expression and activity in prostate cancer." (PMID 35884386, 2022). "As to the mechanisms, levels of the AR in prostate cancer patients are usually upregulated compared to those of normal human prostate tissues." (PMID 36235203, 2022). "Nonetheless, the deregulation of AR-mediated signaling events in the prostate can also trigger the initiation, promotion, and progression of prostate cancer." (PMID 36235203, 2022). "We recapitulate key evidence demonstrating the crosstalk of those pathways as well as with pivotal prostate cancer-related ‘hubs’ such as AR signaling, and evaluate the clinical impact of those interactions." (PMID 35954292, 2022). "The LNCaP cell line constitutes androgen receptor-positive prostate cancer cells that express prostate-specific antigen (PSA) and prostate specific membrane antigen (PSMA), a marker of disease aggressiveness." (PMID 35168543, 2022). "Abnormal AR functioning has been identified in numerous diseases, such as prostatic hyperplasia, prostate cancer, androgen insensitivity syndrome, hypogonadism, or spinal bulbar muscular atrophy." (PMID 35163477, 2022). "Prostate cancer (PC) is the most common cancer in men and is dependent on the Androgen Receptor (AR) signaling for its growth and progression." (PMID 35814399, 2022). "In prostate cancer, tumorigenesis is promoted by androgen through androgen receptor (AR)-mediated gene-expression." (PMID 36072340, 2022). "It potently inhibited cell growth in the LNCaP, VCaP, and 22Rv1 prostate cancer cell lines and was >100 times more potent than the two AR antagonists that were tested." (PMID 35702041, 2022). "Most prostate cancers are androgen-sensitive malignancies whose growths depend on overexpression of the androgen receptor (AR)." (PMID 36497496, 2022).
prostate carcinoma (continued). "An AR activity low stemness program as well as NE differentiation were observed in enzalutamide-resistant prostate cancer cells and tumors." (PMID 34973338, 2022). "Bicalutamide is a competitive androgen receptor antagonist that leads to prostate cell apoptosis and the inhibition of prostate cancer growth." (PMID 35495154, 2022). "Androgen receptor expression has also been investigated as a contributor to the radiation response in multiple types of cancer, including prostate cancer, breast cancer and glioblastoma." (PMID 35618789, 2022). "A large number of studies report that prostate cancer growth as well as progression are driven by the androgen receptor (AR), a ligand-dependent transcription factor as well as a nuclear receptor family member." (PMID 36558146, 2022). "We found that the expression of FKBP51 and FKBP52 in AR‐positive prostate cancer cell lines was greater than that in normal cells and bladder cancer cells." (PMID 34057812, 2022). "Another limitation is the incomplete information about the various interventions employed to antagonize androgen receptor signaling in prostate cancer, such as the dose, duration and frequency of ADT." (PMID 35804979, 2022). "To confirm that ACRJ-PC28 is a prostate cancer cell line, we first examined at the protein level, the presence of prostate specific biomarkers, AR, AMACR, NKX3.1, and PSA." (PMID 36643868, 2022). "The androgen receptor and factors modulating its activity are of great importance in the development of prostate cancer." (PMID 35055079, 2022). "Together, the PI3K-AKT-mTOR pathway and androgen receptor can promote prostate cancer growth and treatment resistance." (PMID 37255653, 2022). "It not only promotes the onset and progression of prostate cancer but also has a clear crosstalk relationship with androgen receptor signals." (PMID 36080361, 2022). "HDACs lead to changes in chromatin accessibility and are important in AR signaling and prostate cancer." (PMID 35909568, 2022). "ERα and AR are members of the nuclear steroid hormone receptor family and play important roles in the development of breast cancer and prostate cancer, respectively." (PMID 35992805, 2022). "AR alterations are rare in systemic therapy-naive prostate cancer, but highly enriched in the castration-resistant disease setting." (PMID 36439451, 2022). "The suppression of the AR signaling remains a significant pathway in the therapy of advanced prostate cancer." (PMID 35751683, 2022). "We found a significant reduction in AR activity in C4-2B FR cells after OCM ABI treatment (p = 0.017) suggesting that ABI inhibited the secretion of OB molecules involved in AR-dependent prostate cancer cell proliferation." (PMID 36140255, 2022). "Prostate cancer (PCa) is primarily a hormone-driven disease mediated by androgen receptor (AR) signaling-driven cell growth." (PMID 35109899, 2022). "A profound suppressive effect was achieved in the prostate cancer xenograft model, together with a significant reduction of the AR protein levels in xenograft tumor tissues." (PMID 35372068, 2022). "Hormone therapy using androgen receptor-signaling inhibitors (ARSi) is a standard treatment for patients with prostate cancer that have either relapsed after surgery and/or radiotherapy or present with metastatic disease at diagnosis." (PMID 36671452, 2022). "Since the AR signaling pathway is critical in prostate cancer development and progression, we analyzed the correlation of TMEM158 expression and AR gene expression in six RNA-seq datasets generated from prostate cancer tissues with different stages." (PMID 36387246, 2022).